FOXH1 (forkhead box H1)
Diseases named in the same sentence as FOXH1 in open-access papers:
FOXH1 is named in the same sentence as 24 diseases in open-access papers, as found by Europe PMC text mining. Sharing a sentence is not in itself a finding about the gene and the disease. The quoted sentences say what the papers report.
breast carcinoma (3 papers, 2019 to 2025). "In contrast, FOXH1 increased the mRNA levels of CTNNB1 and Wnt target genes in breast cancer cell lines, and depletion of β-catenin reversed the positive effects of FOXH1 on tumor cell proliferation and invasion." (PMID 34298659, 2021). "For instance, FOXH1 and FOXQ1 in lung, colorectal, and breast cancer promote EMT by controlling proliferation, migration, and invasion through downregulation of E‐cadherin." (PMID 40099944, 2025).
colorectal cancer (3 papers, 2019 to 2023). A primary or metastatic malignant neoplasm that affects the colon or rectum. "In addition, FOXH1 has been reported to be tightly associated with colorectal cancer progression and could serve as an independent prognostic factor." (PMID 34090445, 2021). "FOXH1 overexpression promotes the proliferation, migration, and invasion of colorectal cancer cells in vivo by down-regulating E-cadherin level." (PMID 34090445, 2021). "The value of FOXD4, FOXH1, and FOXS1 were significantly up-regulated in colorectal cancer relative to the control (FC > 1.5 and P < 0.05)." (PMID 38310407, 2023).
lung carcinoma (3 papers, 2021 to 2023). "Here, we found that the expression of FOXH1 was upregulated in lung cancer cells, and it was associated with a poor prognosis." (PMID 34090445, 2021). "However, the molecular mechanisms underlying the association between FOXH1 expression and lung cancer progression still remain poorly understood." (PMID 34090445, 2021). "Knockdown of FOXH1 significantly inhibited lung cancer cell proliferation, migration, invasion, and cycle." (PMID 34090445, 2021). "The immunohistochemistry staining was applied to determined FOXH1 protein expression levels in the paraffin-embedded lung cancer tissues." (PMID 34090445, 2021). "Knockdown of FOXH1 significantly suppressed the proliferation, migration and invasion of lung cancer cells." (PMID 34090445, 2021). "Further investigation into the mechanism underlying this effect proved that Wnt/β‐catenin signaling pathway was activated by FOXH1 to promote the lung cancer progression." (PMID 34090445, 2021). "The expression of FOXH1 in all the lung cancer cell lines was higher than that in 16HBE normal cell line." (PMID 34090445, 2021). "The Cancer Genome Atlas dataset was used to investigate FOXH1 expression in lung cancer tissues, and the Kaplan–Meier plotter dataset was used to determine the role of FOXH1 in patient prognosis." (PMID 34090445, 2021). "FOXH1 promoted lung cancer progression and metastasis by activating the EMT process and Wnt/β-catenin signaling pathway." (PMID 34090445, 2021). "FOXH1 was effectively knocked down in both sh-FOXH1 transfected lung cancer cell lines and its expression level reduced > 95% 72 h after transfection compared to cells transfected with negative control sh-RNA (sh-NC)." (PMID 34090445, 2021). "The lung cancer patients were stratified into FOXH1 high and FOXH1 low groups using the median of FOXH1 gene expression levels in lung cancer samples." (PMID 34090445, 2021). "FOXH1 knockdown induced significant reduction of TOP/FOP luciferase activity, confirming that the Wnt/β-catenin pathway is a downstream target activated by FOXH1 in lung cancer cells." (PMID 34090445, 2021). "Since A549 and PC9 cell lines simulate lung cancer tissue in terms of the FOXH1 expression level, they were selected for the further experiments." (PMID 34090445, 2021). "Analyses of data from the comprehensive public cancer database TCGA revealed higher expression level of FOXH1 in lung cancer tissues than in normal tissues." (PMID 34090445, 2021). "Based on the results above, we conclude FOXH1 exerts its activity upstream of the β-catenin, and consequently, its silencing inhibits activation of Wnt/β-catenin signaling in lung cancer." (PMID 34090445, 2021). "Our findings indicate that FOXH1 can regulate the metastatic potential of lung cancer cells via activation of EMT." (PMID 34090445, 2021). "Poorer prognosis observed for lung adenocarcinoma patients with higher FOXH1 expression in tumor implies FOXH1 is a prognosis marker and can be a potential treatment target for lung cancer." (PMID 34090445, 2021). "In this study, we found that FOXH1 expression was significantly upregulated in lung cancer tissues and closely related to patient prognosis." (PMID 34090445, 2021). "The mesenchymal markers Matrix metalloproteinase-2 (MMP2), Vimentin, N-cadherin, Snail and Slug were significantly down-regulated, whereas the epithelial markers E-cadherin was notably upregulated by FOXH1 depletion in both lung cancer cell lines." (PMID 34090445, 2021). "Since cancer cell invasion and migration are essential for cancer advancement and malignancy, we investigated how FOXH1 expression affects the mobility of lung cancer cells." (PMID 34090445, 2021). "FOXH1 exerts oncogenic functions in lung cancer through regulation of the Wnt/β-catenin signaling pathway." (PMID 34090445, 2021). "However, the biological functions of FOXH1 in lung cancer progression still remains poorly understood." (PMID 34090445, 2021).
lung carcinoma (continued). "Next, to determine whether FOXH1 is a prognostic marker for lung cancer, we included lung adenocarcinoma samples with patient’s cancer progression and survival data available in TCGA dataset." (PMID 34090445, 2021). "Animal experiments showed that FOXH1 facilitated tumorigenesis of lung cancer in vivo." (PMID 34090445, 2021). "In addition, we observed that knockdown of FOXH1 expression significantly suppressed lung cancer cell proliferation, migration, and invasion." (PMID 34090445, 2021). "However, the detailed biological functions of FOXH1 in lung cancer and the underlying mechanisms have not yet been investigated." (PMID 34090445, 2021). "Our study indicated that targeting FOXH1 might be beneficial to some patients with lung cancer." (PMID 34090445, 2021). "Suppressing FOXH1 expression could effectively inhibit lung cancer cell growth." (PMID 34090445, 2021). "Thus, the main objective of this study is to explore the role of FOXH1 in lung cancer." (PMID 34090445, 2021). "FOXH1 might be a potential therapeutic target for patients with certain types of lung cancer." (PMID 34090445, 2021). "Therefore, the main objective of this study was to explore the role of FOXH1 in lung cancer." (PMID 34090445, 2021). "We demonstrated that FOXH1 activated Wnt/β-catenin signaling, which facilitated the EMT process in lung cancer cells." (PMID 34090445, 2021). "FOXA1 and FOXH1 are members of FOX family of transcription factors, FOXA1 is decreased in hepatocellular carcinoma, FOXH1 promotes cell proliferation, invasion and tumorigenesis by enhancing the Wnt/β-catenin pathway in lung cancer cells and tissues." (PMID 37821907, 2023). "Zhang and colleagues pointed out that forkhead box protein H1 (FOXH1) could encourage EMT through activating the Wnt/β-catenin pathway, thus promoting lung cancer progression." (PMID 34517910, 2021). "CCK8 assays revealed that the proliferation of lung cancer cells was suppressed by FOXH1 silencing while the negative control cells proliferated at the same speed as the un-transfected cells." (PMID 34090445, 2021). "Here, we found that knockdown of FOXH1 significantly decreased the expression of mesenchymal markers (Slug, Snail, MMP2, N-cadherin, and Vimentin), while increasing the expression of epithelial marker (E-cadherin) in lung cancer cells." (PMID 34090445, 2021). "In order to test whether FOXH1 is differentially expressed in lung cancer samples, the normalized gene expression data from TCGA were extracted, and FOXH1 gene expression levels in lung cancer samples were compared with normal tissues using t-tests." (PMID 34090445, 2021). "Representatively, immunohistochemical detection of FOXH1 in the lung cancer and normal lung tissues according to different samples of lung cancer revealed that the immunoreactivity of FOXH1 was barely expressed in surrounding non-tumor and normal lung tissue compared with the tumor." (PMID 34090445, 2021). "The two lung cancer cell lines, PC9 and A549, were transfected with either a sh-RNA specifically targeting FOXH1 (sh-FOXH1) or a negative control sh-RNA (sh-NC), then a Western blot assay was applied." (PMID 34090445, 2021).
pancreatic cancer (2 papers, 2013 to 2025). "Corroborating the GO enrichment of EMT and related pro-metastatic pathways, FOXH1 is an inducer of the TGF-β/Nodal/Activin signaling pathway and has been implicated in proliferation, migration, and invasion of both breast and pancreatic cancer." (PMID 39939916, 2025).
Alzheimer disease (1 paper, 2019). A progressive, neurodegenerative disease characterized by loss of function and death of nerve cells in several areas of the brain leading to loss of cognitive function such as memory and language. "We found that CHRM1 (having putative G4/iMs in first 500 bp upstream), CYP27C1 and FOXH1 (having putative G4/iMs in their first 200 bp upstream) are all linked to pathways related to Alzheimer’s disease." (PMID 31597270, 2019).
lung adenocarcinoma (1 paper, 2021). A carcinoma that arises from the lung and is characterized by the presence of malignant glandular epithelial cells. "The results showed that FOXH1 expression levels are significantly higher in lung adenocarcinoma (p < 0.05), papillary lung carcinoma (p < 0.05) and squamous cell lung carcinoma (p < 0.05) compare to normal samples." (PMID 34090445, 2021). "The mean fold change of FOXH1 expression in lung adenocarcinoma, papillary lung adenocarcinoma and squamous cell lung carcinoma were 0.168, 0.258, and 0.225, respectively." (PMID 34090445, 2021).
medulloblastoma (1 paper, 2019). A malignant, invasive embryonal neoplasm arising from the cerebellum. "Similarly, overexpression of Myc in mouse medulloblastoma cells negatively regulated Foxh1 expression." (PMID 31399583, 2019).
prostate carcinoma (1 paper, 2022). A carcinoma that arises from epithelial cells of the prostate gland. "Accordingly, it has been reported that FOXH1 can act as a hormone-independent corepressor of AR in prostate cancer cells; indeed, a protein-protein interaction was identified between the AR AF-1 domain and FOXH1 independently of the presence of dihydrotestosterone." (PMID 36407312, 2022).
cancer (8 papers, 2014 to 2025). A tumor composed of atypical neoplastic, often pleomorphic cells that invade other tissues. "In particular, TRPV6, ASIC2, MMP13, and FOXH1 are well known to be implicated in cancer development." (PMID 38457049, 2024). "Increased migration of fibroblasts in response to THBS4 stimulation is likely mediated through upregulation of transcription factor FOXH1 that has been shown to promote cancer cell proliferation and migration via activation of Wnt/β-catenin signaling pathway." (PMID 34631719, 2021). "The expression of forkhead box protein H1 (FOXH1) is frequently upregulated in various cancers." (PMID 34090445, 2021). "Recently, a number of studies have reported the role of FOXH1 in various cancers." (PMID 34090445, 2021). "A number of known and previously unknown oncogenes were identified, some of which have already been reported to be associated with cancer, including: ADCY8, ZFAT, BAI1, PTK2, FBXL6, FOXH1, HSF1, and UGT2A1." (PMID 25372838, 2014). "After we identified that the expression of three FOX genes (FOXD4, FOXH1, and FOXS1) are independent prognostic factors and regulate tumor immunity in COAD, we investigated the Spearman’s correlation of these three genes with various cancer-associated pathways activity (R > 0.20 and P < 0.01)." (PMID 38310407, 2023). "Given that HDAC inhibitors increase FOXO1 expression, thereby inhibiting tumor growth, and that silencing FOXO1 dampens this effect, we are tempted to speculate that autophagy and lysosomal biogenesis activated by MiT/TFE and/or FOXH1 may be the pathways of choice for targeted cancer therapy." (PMID 31399583, 2019). "In addition, we investigated the expression variation of these prognostic markers in cancers using the Oncomine database and GSE166427, and found consistent results which ultimately indicate the substantial roles of FOXD4, FOXH1, and FOXS1 incolon cancer." (PMID 38310407, 2023).
tumor (7 papers, 2019 to 2025). "The expression level of FOXH1 was tightly associated with tumor stage, tumor grade and overall survival of HCC." (PMID 35255005, 2022). "Higher expression level of FOXH1 was observed in tumor tissue than in normal tissue, and this was associated with poor overall survival." (PMID 34090445, 2021). "Immunohistochemical staining of mTOR signaling marker, p-S6K1, also confirmed that the tumor promoting role of FOXH1 in HA22T xenografted mouse model was dependent of mTOR activation." (PMID 35255005, 2022). "The experimental evidence also suggested that FOXH1 was truly a tumor promoting factor in HCC progression, strengthening the accuracy of our online analyses." (PMID 35255005, 2022). "The results from orthotopic mouse model also validated that FOXH1 promoted HA22T tumor growth via triggering mTOR activation." (PMID 35255005, 2022). "Collectively, all these in vivo and clinical results demonstrate that FOXH1 serves as a tumor promoting factor controlling HCC tumor development." (PMID 35255005, 2022). "Our study not only pinpoints the clinical value of each FOX protein in HCC but also strengthens the tumor promoting role of FOXH1 with both experimental and clinical evidence." (PMID 35255005, 2022). "Collectively, these results suggested that FOXH1 depletion efficiently suppresses tumor growth in vivo." (PMID 34090445, 2021). "IHC analysis of tumor tissue verified that FOXH1 was barely expressed in the tumor induced by sh-FOXH1transfected cells." (PMID 34090445, 2021). "The proportion of the Ki-67 positive cells was significantly decreased in the tumor induced by FOXH1 depleted A549 cells." (PMID 34090445, 2021). "Our data showed that FOXH1 could enhance HCC cell migration and cell invasion, two essential steps during tumor metastasis, indicating targeting FOXH1 may overcome HCC metastasis." (PMID 35255005, 2022). "Furthermore, knockdown of FOXH1 decreased the expression and secretion of MMP2, a key MMP associated with tumor dissemination and invasiveness." (PMID 34090445, 2021). "Furthermore, FOXH1 binds to Smad2/3 and mediates transforming growth factor beta (TGF-β) signaling, which is associated with tumor development and progression." (PMID 34090445, 2021). "In addition, the mouse xenograft model showed that knockdown of FOXH1 suppressed tumor growth in vivo." (PMID 34090445, 2021). "A mouse xenograft model demonstrated that knocking down FOXH1 inhibited tumor growth in vivo." (PMID 34090445, 2021). "Data showed that FOXH1 indeed could significantly promote HCC tumor growth." (PMID 35255005, 2022). "Furthermore, our in vivo animal data also confirmed that FOXH1 promoted HCC tumor growth." (PMID 35255005, 2022). "First, we found that the stromal scores, immune scores, and tumor purity are significantly deregulated (Wilcoxon sum rank test, P < 0.05) between the HEG and LEG of FOXH1 and FOXS1." (PMID 38310407, 2023). "We found that the FOXH1 and FOXS1 genessubstantially regulate tumor immunity in COAD." (PMID 38310407, 2023). "To test whether FOXH1 promoted HCC progression in vivo, we first orthotopically implanted luciferase-based Vector or FOXH1 HA22T (1X106) into the livers of nude mice and examined tumor growth by using IVIS system." (PMID 35255005, 2022). "Forkhead activin signal transducer 1 (FAST1, FOXH1) is upregulated in RCC and mediates activation of the TGFβ/Smad signaling pathway, leading to increased cell viability, proliferation, migration, invasion, EMT, and reduced apoptosis as well as increased tumor growth." (PMID 37190141, 2023).
FOXH1 also shares sentences with these, for which no sentence is quoted: congenital heart defects (2 papers); Arrhythmia (1); cyclopia (1); female infertility (1); gastric cancer (1); hepatocellular carcinoma (1); infection (1); liver fibrosis (1); major depressive disorder (1); nervous system tumors (1); neuro-degenerative diseases (1); papillary lung adenocarcinoma (1); prostate tumor (1); squamous cell lung carcinoma (1).